CLDN16 (claudin 16)
Description:
Forms paracellular channels: coassembles with CLDN19 into tight junction strands with cation-selective channels through the strands, conveying epithelial permeability in a process known as paracellular tight junction permeability. Involved in the maintenance of ion gradients along the nephron. In the thick ascending limb (TAL) of Henle's loop, facilitates sodium paracellular permeability from the interstitial compartment to the lumen, contributing to the lumen-positive transepithelial potential that drives paracellular magnesium and calcium reabsorption.
Synonyms: PCLN1; HOMG3
Tractability: Antibody: UniProt places it where antibodies can reach, with high confidence; UniProt predicts a signal peptide or a membrane-spanning region; its Gene Ontology location is reachable by antibodies, with medium confidence.
Gene: Protein-coding gene on chromosome 3 (190,322,522 to 190,412,460, forward strand). Ensembl gene ENSG00000113946.
Subcellular location: Cell junction, tight junction; Cell membrane
Pathways (Reactome):
Cell-Cell communication: Tight junction interactions
Gene Ontology:
Molecular function: identical protein binding; paracellular tight junction channel activity; PDZ domain binding; protein binding; magnesium ion transmembrane transporter activity; structural molecule activity
Biological process: paracellular transport; calcium-independent cell-cell adhesion; intercellular transport; intracellular monoatomic cation homeostasis; metal ion transport; magnesium ion transmembrane transport; renal absorption
Cellular component: plasma membrane; tight junction; bicellular tight junction; membrane
Genetic constraint (gnomAD): Loss-of-function variants: 14 observed, 26.14 expected, observed/expected ratio (o/e) 0.54, 90% interval 0.35 to 0.84. The upper end of that interval is the gene's LOEUF score, 0.84, which puts it in group 3 of 6, group 1 being the genes least tolerant of losing a copy. Missense variants: 295 observed, 308.79 expected, observed/expected ratio (o/e) 0.96, 90% interval 0.87 to 1.05. Synonymous variants: 116 observed, 111.91 expected, observed/expected ratio (o/e) 1.04, 90% interval 0.89 to 1.21.
Gene-disease validity (ClinGen):
ClinGen rates the evidence that CLDN16 causes each of these diseases.
renal hypomagnesemia 3 (autosomal recessive): Definitive.
Homologues: Orthologues: chimpanzee CLDN16 (99% identical), macaque CLDN16 (95% identical), dog CLDN16 (94% identical), mouse Cldn16 (92% identical), pig CLDN16 (92% identical), rat Cldn16 (92% identical), rabbit CLDN16 (86% identical), guinea pig CLDN16 (71% identical), tropical clawed frog cldn16 (69% identical). Paralogues in human: CLDN3 (27% identical), CLDN4 (27% identical), CLDN9 (26% identical), CLDN15 (26% identical), CLDN6 (26% identical), CLDN7 (26% identical), CLDN1 (26% identical), CLDN5 (25% identical), CLDN8 (25% identical), CLDN10 (24% identical), CLDN14 (24% identical), CLDN17 (24% identical), and 10 more.
Diseases named in the same sentence as CLDN16 in open-access papers:
CLDN16 is named in the same sentence as 53 diseases in open-access papers, as found by Europe PMC text mining. Sharing a sentence is not in itself a finding about the gene and the disease. The quoted sentences say what the papers report.
Hypercalciuria (41 papers, 2008 to 2025). "In the present study, homozygous mutations of the CLDN16 gene were detected in a 20-year-old female who was clinically diagnosed with hypomagnesemia, hypocalcemia, hypercalciuria, bilateral nephrocalcinosis, and CKD stage G4." (PMID 40428323, 2025). "Patients with mutations in Cldn16 suffer from familial hypomagnesaemia with hypercalciuria and nephrocalcinosis (FHHNC) which can lead to renal insufficiency." (PMID 38339056, 2024). "Mutations in CLDN16 and − 19 also cause hypomagnesemia, associated with hypercalciuria and nephrocalcinosis (HOMG3 and 5)." (PMID 39614204, 2024). "Renal hypomagnesemia 3 (OMIM phenotype number 248250) is an AR condition due to inactivating variants in CLDN16, resulting reduced reabsorption of calcium (hypercalciuria)and magnesium (hypermagnesuria) with hypomagnesemia, NC, NL, and progressive CKD." (PMID 38606357, 2024). "Mutations in CLDN16 and CLDN19cause familial hypomagnesemia with hypercalciuria and nephrocalcinosis (FHHNC),demonstrating their involvement in Mg2+ reabsorption." (PMID 38871680, 2024). "This physical coupling is highlighted by the fact that the loss of either claudin-16 or claudin-19 results in the same disease, familial hypomagnesemia with hypercalciuria and nephrocalcinosis." (PMID 34810264, 2021). "So far, 3 claudins (10b, 16 and 19) have been causally traced to rare human syndromes: variants of CLDN10b cause HELIX syndrome and variants of CLDN16 or CLDN19 cause familial hypomagnesemia with hypercalciuria and nephrocalcinosis." (PMID 32164158, 2020). "Familial hypomagnesemia with hypercalciuria and nephrocalcinosis is an autosomal recessive disorder caused by variants of the CLDN16 (OMIM #248250) and CLDN19 (OMIM #248190) genes." (PMID 32164158, 2020). "Mutations in human CLDN16 cause an autosomal recessive disorder called Familial hypomagnesemia with hypercalcinuria and nephrocalcinosis (FHHNC)." (PMID 31694170, 2019). "Familial hypomagnesemia with hypercalciuria and nephrocalcinosis (FHHNC) is a rare autosomal recessive disorder caused by mutations in either CLDN16 or CLDN19 genes." (PMID 30305086, 2018). "Sixty mutations of claudin 16 coding gene have been reported in familial hypomagnesemia with hypercalciuria and nephrocalcinosis (FHHNC) patients." (PMID 30005619, 2018). "A mouse model of Cldn16 deficiency resulted in serum hypomagnesaemia and hypercalciuria; however, structural defects of the kidney and urinary bladder were not reported." (PMID 26398943, 2015). "This study provides the first report of a large homozygous deletion in the CLDN16 gene causing familial hypomagnesemia with hypercalciuria and nephrocalcinosis with late onset of the first symptoms." (PMID 26136118, 2015). "Mutations in CLDN16 (alias PCLN1) cause the autosomal recessive condition familial hypomagnesaemia with hypercalciuria and nephrocalcinosis (FHHNC)." (PMID 24321194, 2013). "FHHNC patients and animal models with claudin-16 or claudin-19 mutations are known to have hypercalciuria, nephrocalcinosis, and nephrolithiasis." (PMID 23799361, 2013). "Mutations in the claudin genes, claudin-16 and claudin-19, cause familial hypomagnesemia with hypercalciuria and nephrocalcinosis (FHHNC)." (PMID 23799361, 2013). "Mutations in CLDN16 underlie familial hypomagnesaemia with hypercalciuria and nephrocalcinosis but remain a rare cause of nephrocalcinosis and nephrolithiasis." (PMID 24321194, 2013). "A CLDN16 missense mutation (Thr233Arg) has also been identified in two families with self-limiting childhood hypercalciuria." (PMID 18446382, 2009). "Mutations in Cldn16 or Cldn19 that encode claudin-16 and claudin-19, respectively, cause familial hypomagnesemia with hypercalciuria and nephrocalcinosis (FHHNC) (OMIM: 248250), which is an autosomal-recessive renal tubular disorder which sees nephrocalcinosis as a main symptom." (PMID 38339056, 2024).
Hypercalciuria (continued). "Data suggests that carriers (heterozygotes) of inactivating variants in CLDN16 may have hypercalciuria and NL." (PMID 38606357, 2024). "Paracellular Ca2+ reabsorption is better characterized in the thick ascending limb, in which claudin-16 and claudin-19 form Ca2+ permeable pores and mutations in these genes cause the syndrome familial hypomagnesemia with hypercalciuria and nephrocalcinosis associated with severe renal Ca2+ wasting." (PMID 34810264, 2021). "In their study, they reported that the mutations in the human gene, paracellin-1 (PCLN-1)/CLDN-16 causes an autosomal recessive disorder called Familial hypomagnesemia with hypercalcinuria and nephrocalcinosis (FHHNC) characterized with renal Mg2+ and Ca+ wasting." (PMID 31952355, 2020). "Another finding that should be commented upon, pertaining to the CLDN16 gene interaction network, is the identification of the CLDN10 gene as recently it was reported that deletion of the latter rescues CLDN16-deficient mice from hypomagnesemia and hypercalciuria." (PMID 31357502, 2019). "In addition, mice with CLDN10 deletion in the thick ascending limb show the impairment in paracellular Na+ permeability and hypermagnesemia, and can rescue CLDN16-deficient mice from hypomagnesemia and hypercalciuria." (PMID 31382627, 2019). "Therefore, it has been reported that downregulation of claudin-16 might be the cause of hypermagnesuria and hypercalciuria." (PMID 39684861, 2024). "Claudin-16 inactivating mutations in humans are associated with hypercalciuria and nephrocalcinosis, possibly suggesting that significantly reduced claudin-16 expression in our studies might have contributed to the phenotype of vitamin D3-treated Npt2a−/− mice." (PMID 39043847, 2024). "Loss of Claudin 1 function mutations could result in neonatal ichthyosis-sclerosing cholangitis syndrome, while the gene mutations in CLDN16 could cause familial hypomagnesemia with hypercalciuria and nephrocalcinosis (FHHNC) which is a rare autosomal recessive renal disease." (PMID 29467824, 2018). "We also evaluated the expression of Cldn16 and Cldn19, since their crucial role in ameloblast tight-junction formation has been recently indicated; their mutation causing familial hypomagnesaemia with hypercalciuria and nephrocalcinosis and amelogenesis imperfecta." (PMID 29375389, 2017). "Familial hypomagnesemia with hypercalciuria and nephrocalcinosis (FHHNC) is a rare autosomal recessive renal tubular disorder caused by mutations in the CLDN16 or CLDN19 genes." (PMID 40826740, 2025). "Human CLDN16 and CLDN19 variants are associated with familial hypomagnesemia with hypercalciuria (FHHNC; OMIN 248250), and a missense variant in CLDN19 has been associated with NTDs." (PMID 37377737, 2023). "Mutations in claudin 16 and 19 (familial hypomagnesemia with hypercalciuria and nephrocalcinosis, FHHNC), result in hypercalciuria, nephrocalcinosis, nephrolithiasis and renal failure." (PMID 35299844, 2021). "For example, mutations in six of the amelogenesis imperfecta-associated genes (CLDN16, CLDN19, FAM20A, KCNJ1, SLC4A1, and WDR72) are associated with nephrocalcinosis, hypercalciuria, and renal failure." (PMID 33672174, 2021). "For example, mutations in CLDN16 and CLDN19 in humans resulted in kidney disorders exhibiting renal magnesium wasting and hypercalciuria." (PMID 31382627, 2019). "In 1999, the group of Lifton showed that the disorder Familial Hypercalciuria, Hypomagnesemia with Nephroclacinosis (FHHNC) is caused by mutations in the CLDN16 gene." (PMID 31694170, 2019). "The late-onset chronic kidney disease in the presence of a homozygous deletion in the CLDN16 gene reinforces the great variability of genotype-phenotype manifestation in patients with familial hypomagnesemia with hypercalciuria and nephrocalcinosis." (PMID 26136118, 2015).
Hypercalciuria (continued). "CLDN16, encoding claudin-16/paracellin-1, and CLDN19, encoding claudin-19, are mutated in recessive familial hypomagnesemia with hypercalciuria and nephrocalcinosis." (PMID 24339795, 2013). "We report a large consanguineous family who presented with a variety of clinical and biochemical features suggestive of familial hypomagnesaemia with hypercalciuria and nephrocalcinosis (FHHNC) in whom we have identified a novel homozygous CLDN16 mutation." (PMID 24321194, 2013). "Familial hypomagnesemia with hypercalciuria and nephrocalcinosis (FHHNC) is an ultra-rare autosomal recessive renal tubular disease with an incidence of <1/1.000.000 individuals, caused by loss-of-function mutations in CLDN16 and CLDN19." (PMID 40173198, 2025). "Familial hypomagnesemia with hypercalciuria and nephrocalcinosis (FHHNC) is an ultra-rare autosomal recessive renal tubular disease with an incidence of less than 1 in 1,000,000 individuals, caused by loss-of-function mutations in CLDN16 and CLDN19." (PMID 40173198, 2025). "Since CaSR is suggested to promote urine acidification and diuretic effects in response to hypercalciuria in Trpv5 KO mice, changes in the activation level of this receptor due to changes in hormonal response can lead to different overall responses in Cldn16 KO mice." (PMID 38339056, 2024). "Likewise, whereas Trpv5 KO mice showed hypercalciuria only, Cldn16 KO mice showed hypercalciuria accompanied by hypermagnesuria." (PMID 38339056, 2024). "The difference is hormonal response between Cldn16 KO and Trpv5 KO mouse models can account for different activation levels of CaSR in the collecting duct, therefore resulting in the different responses to hypercalciuria." (PMID 38339056, 2024). "Mutations in CLDN16 and CLDN19, which encode the tight junction proteins claudin-16 and claudin-19 respectively, give rise to the condition familial hypomagnesaemia with hypercalciuria and nephrocalcinosis (FHHNC)." (PMID 31935940, 2020). "Hydrochlorothiazide has been shown to be effective in correcting hypercalciuria due to CLDN16 mutations in some but not all patients." (PMID 32164158, 2020). "By deleting the Cldn16 gene, we have generated a FHHNC mouse model displaying hypomagnesemia and hypercalciuria comparable to the patient situation." (PMID 38339056, 2024). "Mutations affecting the paracellular Mg2+transport pathway in the TAL (CLDN16, CLDN19, RRAGD, CASR)results in the hypomagnesemia with hypercalciuria and nephrocalcinosis." (PMID 38871680, 2024). "Mice lacking Cldn16 develop hypercalciuria and hypomagnesemia, which is similar to the phenotype of patients with familial hypomagnesemia with hypercalciuria and nephrocalcinosis (FHHNC) that carry pathogenic variants in CLDN1650." (PMID 33850129, 2021). "Mice lacking claudin-16 show hypomagnesemia and hypercalciuria, but no nephrocalcinosis." (PMID 38339056, 2024).
nephrocalcinosis (35 papers, 2008 to 2025). Nephrocalcinosis is a disorder that occurs when too much calcium is deposited in the kidneys. "Nephrocalcinosis is often caused by defects in renal epithelial transport including mutations in Cldn16, Cldn19, Clcn5 and Slc34A1." (PMID 38339056, 2024). "In summary, in we have made a molecular genetic diagnosis of a CLDN16 mutation in a large consanguineous family with nephrocalcinosis, renal stones and renal impairment." (PMID 24321194, 2013). "In the present study, we tested the hypothesis that urine acidification by vesicular H+ ATPase prevents nephrocalcinosis in claudin-16-deficient mice." (PMID 38339056, 2024). "A few reports mention distal defect of urinary acidification: incomplete distal renal tubular acidosis may affect up to 80% of patients but it remains unclear whether it is directly caused by CLDN16/19 mutation or by nephrocalcinosis." (PMID 32164158, 2020). "The difference in phenotype between Trpv5 Atp6v1b1 dKO and Cldn16 Atp6v1b1 dKO extends beyond nephrocalcinosis." (PMID 38339056, 2024). "There are differences between the Trpv5 KO model and our Cldn16 KO model in the context of nephrocalcinosis." (PMID 38339056, 2024). "Background and Objectives: The defects in the CLDN16 gene are a cause of primary hypomagnesemia (FHHNC), which is characterized by massive renal magnesium wasting, resulting in nephrocalcinosis and renal failure." (PMID 31357502, 2019). "Assuming that urine acidification is causative for the absence of nephrocalcinosis in the claudin-16-deficient mouse model, we aimed to alkalinize the urine of these mice by the ablation of the subunit B1 of the vesicular ATPase in addition to claudin-16." (PMID 38339056, 2024). "The molecular cause for CLDN16 dominance remains unexplained, but it is also reflected in the widespread expression of CLDN16 at all cell borders when CLDN10 is deleted in mice and in human HELIX syndrome, in which mutations in CLDN10 lead to hypermagnesemia and nephrocalcinosis." (PMID 40471686, 2025). "Thus, urinary acidification is not the only factor preventing nephrocalcinosis in claudin-16 deficient mice." (PMID 38339056, 2024). "In spite of an increased urinary pH in mice lacking claudin-16 and the B1 subunit, nephrocalcinosis did not develop." (PMID 38339056, 2024). "By showing that urine alkalinization does not induce nephrocalcinosis in hypercalciuric mice lacking claudin-16 due to the deletion of Atp6v1b1, we emphasize the multifactorial nature of this pathology." (PMID 38339056, 2024). "Von Kossa staining and Alizarin Red S staining showed the absence of nephrocalcinosis in Cldn16 KO male and in Cldn16 Atp6v1b1 dKO counterpart mice." (PMID 38339056, 2024). "This conclusion is based on the absence of nephrocalcinosis despite the urine alkalinization induced by the additional deletion of the Atp6v1b1 gene in the Cldn16 Atp6v1b1 dKO model." (PMID 38339056, 2024). "In this study, we demonstrate that urine acidification is not the main reason behind the absence of nephrocalcinosis in the Cldn16 KO mouse model." (PMID 38339056, 2024). "In contrast to Trpv5 Atp6v1b1 dKO, in our Cldn16 Atp6v1b1 dKO the alkalinization in the urine did not lead to nephrocalcinosis." (PMID 38339056, 2024). "Mice lacking claudin-16 and claudin-10 in the kidney were found to have normal Mg2+ in serum and absence of nephrocalcinosis." (PMID 31694170, 2019). "In addition, these animals did not develop nephrocalcinosis and kidney failure, suggesting that there may be compensatory mechanisms in this model that cause calcium and magnesium homeostasis in the absence of claudin-16." (PMID 26136118, 2015).
Hypomagnesemia (21 papers, 2013 to 2025). An abnormally decreased magnesium concentration in the blood. "In 2010, a study using Cldn16 knockout mice yielded interesting results concerning the age of onset of hypomagnesemia." (PMID 26136118, 2015).
renal failure (7 papers, 2013 to 2025). "Eight patients (14.81%) developed kidney failure requiring kidney replacement therapy; CLDN16 was significantly associated with kidney failure and transplant (P = 0.003), and AGXT with liver transplant (P < 0.001)." (PMID 41203986, 2025). "Konrad and colleagues have suggested a genotype‐phenotype correlation related to the progression of renal failure in FHHNC patients with CLDN16 mutations." (PMID 32869508, 2020). "Additionally, Konrad and colleagues have established a genotype-phenotype correlation with regard to the progression of renal failure in FHHNC patients with CLDN16 mutations." (PMID 23301036, 2013). "This means that the losses of function and expression of CLDN16 may not be a cause of renal failure." (PMID 31273276, 2019).